FMR1 (fragile X messenger ribonucleoprotein 1)
Diseases named in the same sentence as FMR1 in open-access papers (continued):
Sharing a sentence is not in itself a finding about the gene and the disease.
frontotemporal dementia (7 papers, 2013 to 2023). Frontotemporal dementia (FTD) comprises a group of neurodegenerative disorders, characterized by progressive changes in behavior, executive dysfunction and language impairment, as a result of degeneration of the medial prefrontal and frontoinsular cortices. "However, changes in several other genes have been suggested as causes for recessive neurological/neurodegenerative disorders that may include PD: hereditary ataxias (ATXN2/3, FMR1), frontotemporal dementia (e.g. MAPT) and others (e.g. ATP13A2, PLA2G6, FBXO7)." (PMID 23976986, 2013).
melanoma (7 papers, 2017 to 2025). A malignant, usually aggressive tumor composed of atypical, neoplastic melanocytes. "A comparative analysis of the transcriptome of two FMRP-depleted melanoma cells (FMR1 siRNA) versus CTR was performed." (PMID 29144507, 2017). "Moreover, a meta-analysis of The Cancer Genome Atlas (TCGA) melanoma data set revealed that increased FMR1 expression level significantly correlates with metastatic melanoma, risk of tumor relapse and reduced disease-free survival." (PMID 29144507, 2017). "Moreover, a survival analysis, comparing high- and low-expressing FMR1 primary melanoma (N=47), showed a significant decreased disease-free survival in patients with FMR1-overexpressing tumors." (PMID 29144507, 2017). "Accordingly, an in silico analysis of a melanoma cohort (402 patients) from publicly accessible TCGA data set (RNA-sequence (RNA-seq) data) showed that increased FMR1 mRNA expression level significantly correlated with metastatic melanoma and risk of tumor relapse." (PMID 29144507, 2017). "Comparing primary melanoma and metastases, we found that ALKBH5, ELAVL1, FMR1, HNRNPA2B1, HNRNPC, IGF2BP1/2/3, KIAA1429, LRPPRC, RBM15, YTHDC1/2, YTHDF1/3, and ZC3H13 were significantly upregulated in metastases, while RBM15B and METTL3 were significantly upregulated in primary melanoma." (PMID 34993195, 2021). "The survival rate of both melanoma cell lines in the three experimental conditions (CTR, scr siRNA or FMR1 siRNA) did not change, excluding an important effect of FMRP on proliferation and/or cell death." (PMID 29144507, 2017). "To verify whether lack of FMRP might lead to different capacity of melanoma cells to migrate, invade and/or adhere, we knocked down FMRP expression in 501 mel or A375 cells, treating the cells for 24, 48 or 72 h with a scrambled or specific small interfering RNAs (siRNAs) (FMR1 siRNA)." (PMID 29144507, 2017).
Turner syndrome (7 papers, 2017 to 2025). Turner syndrome is a chromosomal disorder associated with the complete or partial absence of an X chromosome. "After Turner syndrome, fragile X mental retardation 1 (FMR1) is the most common congenital cause of POI (2–5% of women with POI)." (PMID 41226870, 2025). "Apart from Turner’s syndrome, the FMR1 premutation is the most common known congenital cause of POI." (PMID 38760837, 2024). "The most common genetic causes of POI are Turner syndrome, premutation in the fragile X messenger ribonucleoprotein 1 (FMR1) gene, somatic and X chromosome gene defects (FOXL2, eIF4ENIF1, STAG3, NR5A1, BMP15, FSHR, Gs alpha, and steroidogenic enzymes)." (PMID 35813658, 2022). "When this is the case, the underlying pathogenetic mechanism of follicle depletion are heterogeneous ranging from genetic (Turner’s syndrome, mutations in the genes FMR-1, BMP-15, Foxl2, and recently identified MCM9, SYCE1, STAG3) to auto-immune and iatrogenic causes." (PMID 29176793, 2017).
bipolar disorder (6 papers, 2013 to 2022). A disorder of the brain that causes unusual shifts in mood, energy, activity levels and the ability to carry out day-to-day tasks. "Noticeably, PM carriers showing both FMR1 mRNA increase and FMRP decrease may develop psychotic and bipolar disorder features that are extremely rare in FXTAS and FXS patients, probably due to a synergistic effect of the gain- and loss-of-function components of CGG expansion." (PMID 34445074, 2021).
memory impairment (6 papers, 2015 to 2026). "Building on existing tools and substantial knowledge of Fmr1, our research may open new avenues for the study of AD‐associated cognitive decline and memory impairment from the effects of Fmr1." (PMID 35434801, 2022). "Our data are novel and may provide mechanisms of hypoxia-induced impairments in the spatial memory and action of CDRI-08 in the recovery of hypoxia led memory impairment involving Fmr-1 gene encoded protein called FMRP." (PMID 26413121, 2015). "In passive avoidance, we find that Fmr1 KO/Fxr2 Het mice have more profound learning and memory impairments than do the other genotypes studied." (PMID 30654445, 2019). "Like FMRP, FXR2P is expressed in brain with a similar regional distribution and mice deficient in FXR2P (Fxr2 KO) exhibit some of the same behavioral deficits seen in Fmr1 KO mice such as hyperactivity and learning and memory impairments." (PMID 30654445, 2019). "Deficiencies in the fragile X messenger ribonucleoprotein, encoded by the FMR1 gene, lead to various anatomical and pathophysiological abnormalities and behavioral deficits, such as spine dysmorphogenesis and learning and memory impairments." (PMID 39022311, 2024). "Fmr1 KO/Fxr2 Het mice have more severe learning and memory impairments than Fmr1 KO mice." (PMID 30654445, 2019). "However, the role of Bacopa monnieri extract (CDRI-08) in enhancing cognitive abilities in hypoxia-induced memory impairment via Fmr-1 gene expression is not known." (PMID 26413121, 2015).
neuroblastoma (6 papers, 2016 to 2024). Neuroblastoma (NB) is the most common solid, extracranial childhood tumor. "Consequently, we used mouse N2A neuroblastoma cells depleted of Fmr1 by an siRNA complementary to this RNA’s 3′ UTR, which reduced FMRP levels by >95% compared to a nontargeting (NT) control." (PMID 38048343, 2023). "Thus, it remains to be established what role FMR1 has in neuroblastoma tumorigenesis." (PMID 27448979, 2016).
behavioral disorders (5 papers, 2019 to 2023). "In addition, cholesterol depletion by Mβ-CD recovers AMPA receptor trafficking and ameliorates the principal behavioral disorders observed in Fmr1 KO mice." (PMID 36854997, 2023). "Our results indicated that ICAM5 knockdown reversed behavioral disorders in Fmr1 KO mice." (PMID 31882402, 2020). "DHT supplementation post-castration reversed the alterations in density and maturity of dendritic spines of hippocampal neurons and behavioral disorders in WT mice; however, it did not reveal such effects in Fmr1 KO mice." (PMID 35530178, 2022). "Lack of FMRP in the Fmr1 KO mouse neurons results in the loss of Dgkκ expression along with mGluR1 receptor-dependent DGK activity, leading to synaptic plasticity alterations, dendritic spine abnormalities, and behavior disorders." (PMID 31035599, 2019).
clear cell renal cell carcinoma (5 papers, 2023 to 2025). "Fragile X mental retardation 1 (FMR1) has been identified as a new immune-related prognostic biomarker for renal clear cell carcinoma." (PMID 37302999, 2023). "In clear cell renal cell carcinoma, estrogen receptor β (ERβ) upregulates circAHNAK, which competitively binds USP10 to prevent FMR1 deubiquitination, leading to FMR1 degradation." (PMID 41058008, 2025). "Conversely, FMR1 was downregulated in glioblastoma multiforme (GBM, P < 0.05), kidney clear cell carcinoma (KIRC, P < 0.001), kidney papillary cell carcinoma (KIRP, P < 0.001), prostate adenocarcinoma (PRAD, P < 0.001), and uterine corpus endometrial carcinoma (UCEC, P < 0.001)." (PMID 41184982, 2025).
ovarian carcinoma (5 papers, 2012 to 2022). A malignant neoplasm originating from the surface ovarian epithelium. "Only the Israeli study, therefore, like here reported ovarian cancer data, reported an actually inverted picture of more low FMR1 alleles in BRCA1/2-negative than BRCA1/2-positive women." (PMID 25036526, 2014). "This study for the first time investigated the alleged BRCA1/2 interaction with low FMR1 mutations in an ovarian cancer model." (PMID 25036526, 2014). "The mechanism of BRCA/FMR1 mutation causing ovarian cancer deserves further study." (PMID 34187307, 2021). "We in this study investigated in women with various forms of ovarian cancer whether the presence of BRCA1/2 mutations resulted in enrichment of low FMR1 mutations, which would suggest interplay between these two genes, in establishing oncogenic risk." (PMID 25036526, 2014). "Both analyses, thus, demonstrate that the combined presence of BRCA1/2 mutations and low FMR1 alleles actually appears to be less commonly associated with ovarian cancer than absence of both of these mutations in the same patient." (PMID 25036526, 2014). "Indeed, this study actually demonstrated the opposite, a normal-range prevalence of low FMR1 alleles in BRCA1/2 mutation-carrying ovarian cancer patients but a trend towards higher prevalence in ovarian cancer patients who were not BRCA1/2 carriers." (PMID 25036526, 2014). "FMR1 may be involved in the regulation of ATR-dependent signaling pathways such as BRCA1 phosphorylations and interact with BRCA in human Ovarian Cancers." (PMID 30286182, 2018). "When the same analysis was repeated for only 15 functionally oncogenic BRCA1/2 mutations, outcomes were very similar, 2/15 (13.3%) low FMR1 alleles in BRCA1/2 mutation carriers and 21/65 (32.3%) in ovarian cancer patients without BRCA1/2 mutations (P = 0.21)." (PMID 25036526, 2014). "The expression of the m6A RNA methylation regulator in ovarian cancer patients with and without BRCA1 mutation was also analyzed, and it has been found that the expression of both FMR1 and YTHDF1 showed differences between BRCA1-mutation and non-BRCA1-mutation groups (SupportingFigure 5)." (PMID 34187307, 2021).
attention deficit-hyperactivity disorder (4 papers, 2022 to 2025). A disorder characterized by a marked pattern of inattention and/or hyperactivity-impulsivity that is inconsistent with developmental level and clearly interferes with functioning in at least two settings (e.g. at home and at school). "In other expansion diseases, such as in premutation carriers in at the FMR1 locus, a high level of somatic instability has been associated specifically with the presence of neuropsychiatric symptoms, such as attention deficit hyperactivity disorder (ADHD)." (PMID 38448560, 2024). "5-HT5A antagonists reduced hyperactivity and improved cognition in Fmr1 KO rats, and thus might be used in Fragile X patients with concomitant attention deficit and hyperactivity disorder (ADHD)." (PMID 40141138, 2025).
female infertility (4 papers, 2018 to 2025). Diminished or absent ability of a female to achieve conception. "Our study represents the first investigation of the association between the pattern of AGG interruption at the FMR1 alleles and female infertility." (PMID 40600017, 2025). "Low FMR1 variants (CGGn<26) have been associated with premature ovarian aging, female infertility and poor IVF treatment success." (PMID 30576349, 2018). "FMR1 gene is the most prominent candidate gene of POI, as a consequence, it has been postulated that a relationship exists between FMR1 gene and female infertility." (PMID 40600017, 2025). "The higher and lower CGG repeats on the FMR1 gene denote similar risks toward premature ovarian senescence and female infertility." (PMID 33763463, 2021). "Further investigation of these changes should lead to an improved understanding of contributions of the FMR1 gene to physiologic and premature ovarian aging and female infertility." (PMID 30576349, 2018). "However, there is relatively little published studies on the effects of FMR1 CGG repeat size on female infertility, especially in the Asian population." (PMID 40600017, 2025). "Further investigation of these changes could elucidate the contribution of FMR1 to physiological and premature ovarian aging and female infertility." (PMID 39408972, 2024).
fibromyalgia (4 papers, 2014 to 2025). A chronic disorder of unknown etiology characterized by pain, stiffness, and tenderness in the muscles of neck, shoulders, back, hips, arms, and legs. "The association between Fibromyalgia (FM) and the FMR1 gene premutation has been suggested, but remains inconclusively established." (PMID 40916316, 2025). "•The preliminary data suggest an association between the FMR1 gene premutation and susceptibility to Fibromyalgia (FM), but larger studies with consistent designs are needed to confirm this hypothesis." (PMID 40916316, 2025). "Several chronic pain syndromes prevalent in female FMR1 premutation carriers are comorbid with migraine including fibromyalgia, allodynia, and chronic fatigue syndrome, suggesting diffuse alterations to the nociceptive nervous system." (PMID 35126193, 2021).
glioblastoma (4 papers, 2022 to 2025). The most malignant astrocytic tumor (WHO grade IV). "This novel feedback loop between FMR1, circCHAF1A, miR-211-5p, and HOXC8 in glioblastoma stem-like cells can promote glioma proliferation and tumorigenesis." (PMID 40271197, 2025).
glioma (4 papers, 2020 to 2025). A benign or malignant brain and spinal cord tumor that arises from glial cells (astrocytes, oligodendrocytes, ependymal cells). "Unexpectedly, FMR1, EIF3A, and ZC3H13, whose high expressions indicated poor prognosis, were up-regulated in the IDH mutant and 1p19q codeletion gliomas since the two genomic mutations indicated favorable prognoses." (PMID 33240891, 2020).
Hunter syndrome (4 papers, 2011 to 2024). "IDS deletions are found in some Hunter syndrome patients, and a more severe Hunter phenotype has been reported in patients with larger deletion regions that include FMR1." (PMID 23634718, 2013).
learning disabilities (4 papers, 2012 to 2023). "Examples are the leukaemia-protecting histone demethylase KDM6A, FMR1, a gene linked to Fragile-X and learning disability, and the Duchenne muscular dystrophy gene DMD." (PMID 36802379, 2023).
mental disorder (4 papers, 2016 to 2024). A disease that has its basis in the disruption of mental process. "EMA studies suggested that this might include patients suffering from mental disorders, spinal cord injury, 22q11.2 deletions syndrome and women carrying a premutation of FMR1." (PMID 35895674, 2022).
amenorrhea (3 papers, 2024). The absence of menses in a woman who has achieved reproductive age. "A minimal effect of FMR1 allelic complexity with age at amenorrhea is observed in balanced allelic scores." (PMID 38907244, 2024).
bladder cancer (3 papers, 2022 to 2023). "Of note, two identified treatment outcome-related genes, FMR1 and HNRNPA2B1, are found in the turquoise module, indicating the important role of these two m6A regulators in the immunotherapy of bladder cancer." (PMID 36189296, 2022). "However, we found that expression of FMR1 and HNRNPA2B1 were not correlated with the overall survival in bladder cancer patients based on TCGA-BLCA dataset, who were not treated with immunotherapy." (PMID 36189296, 2022).
cervical cancer (3 papers, 2022 to 2025). A primary or metastatic malignant neoplasm involving the cervix. "In cervical cancer (CESC), FMR1 and ZC3H13 emerged as key regulators." (PMID 40565233, 2025).
Cowden syndrome (3 papers, 2017 to 2023). "An increased Akt/mTOR activity is consistent with deficiencies of FMR1, TSC1/2, or PTEN found in Fragile X, TSC, and Cowden syndrome, respectively." (PMID 28361047, 2017). "Increased Akt/mTOR activity is consistent with deficiencies of FMR1, TSC1/2, or PTEN found in Fragile X, TSC, and Cowden syndrome and suggests that increased Akt/mTOR activity may have a role in the pathophysiology of the general ASD population and not limited to single ASD genetic mutations." (PMID 28361047, 2017).
cystic fibrosis (3 papers, 2009 to 2015). Autosomal recessive disorder caused by pathogenic variants in the CFTR gene (cystic fibrosis transmembrane conductance regulator), which encodes a chloride and bicarbonate channel expressed in epithelial cells, and follow the diagnosis criteria. "In particular, for molecular genetic testing, it offers specific EQA schemes for 4 diseases: Cystic Fibrosis (CFTR gene), Beta Thalassemia (HBB gene) (BT), Fragile X-Syndrome (FMR1 gene) (FX), and Familial Adenomatous Polyposis Coli (APC gene) (APC)." (PMID 23484150, 2013).
esophageal squamous cell carcinoma (3 papers, 2022 to 2023). Esophageal squamous cell carcinoma (ESCC) is a type of esophageal carcinoma (EC) that can affect any part of the esophagus, but is usually located in the upper or middle third. "Besides, elevated expression of FMR1 was regarded as a pathogenic target in promoting cell proliferation in esophageal squamous cell carcinoma (ESCC); the positive feedback loop HNF4α-BC200-FMR1 is also necessary in promoting invasive mucinous lung adenocarcinoma (IMA) progression and metastasis." (PMID 37732317, 2023).
lung carcinoma (3 papers, 2021 to 2025). "Based on this prediction, we assessed FMR1 expression in H1299 and A549 lung cancer cells after co-incubation with exosomes (containing PITPNA-AS1), and found that FMR1 protein expression was strikingly elevated." (PMID 40342419, 2025). "In addition, it was found to be involved in lung cancer progression by inhibiting FMR1 ubiquitination." (PMID 40342419, 2025). "Therefore, we speculate that the involvement of lncRNA PITPNA-AS1 in the progression of lung cancer may be mediated by FMR1." (PMID 40342419, 2025). "In this study, the validated interaction between lncRNA PITPNA-AS1 and FMR1 in lung cancer was first presented, with lncRNA PITPNA-AS1 upregulation increasing FMR1 levels." (PMID 40342419, 2025). "To evaluate the expression profile of m6A readers in lung cancer, we analyzed known readers, including YTHDF1/2/3, YTHDC1/2, HNRNPA2B1, HNRNPC/G, eIF3A, FMR1 and IGF2BP1/2, in LUAD and lung squamous cell carcinoma (LUSC) via the GEPIA database." (PMID 33232910, 2021). "Although FMR1 has been reported to be involved in cancer progression, an in-depth exploration of its biological function will contribute to understand the mechanism of lncRNA PITPNA-AS1-mediated proliferation and metastasis in lung cancer." (PMID 40342419, 2025).
lung squamous cell carcinoma (3 papers, 2016 to 2025). "FXR1 is a member of the Fragile X-related family of RNA-binding proteins, which also includes Fragile X Mental Retardation 1 (FMR1) and FXR2 and is frequently amplified in lung squamous cell carcinoma." (PMID 27812105, 2016).
polycystic ovary (3 papers, 2010 to 2018). "The FMR1 gene partially appears to control ovarian reserve, with a specific ovarian sub-genotype statistically associated with a polycystic ovary (PCO)- like phenotype." (PMID 21179569, 2010).
viral infection (3 papers, 2019 to 2025). "Pregnant heterozygous Fmr1 mouse females were exposed to maternal immune activation (MIA), by injecting the immunostimulant Poly (I:C) at the embryonic stage 12.5, simulating viral infections." (PMID 39604505, 2025). "To control for the possibility that virus infection per se affects spine density, we also measured spine density in Thy1-GFP-M mice (which are Fmr1+, hence denoted “WTM”) as well as in GKO × Thy1-GFP-M (“GKOM”) mice." (PMID 37035256, 2023).
asthma (2 papers, 2022 to 2024). "Moreover, another study on childhood asthma found that m6A regulators also played a crucial role and screened five candidate m6A regulators (FMR1, KIAA1429, WTAP, YTHDC2, and ZC3H13) to predict the risk of childhood asthma." (PMID 35712670, 2022).